CMKLR1 (chemerin chemokine-like receptor 1)
Diseases named in the same sentence as CMKLR1 in open-access papers (continued):
Sharing a sentence is not in itself a finding about the gene and the disease.
tumor (continued). "It is particularly noteworthy that 6 chemokine receptors in GO term “chemokine binding”, including CXCR4, CCR5, CCR1, CCRL2, CMKLR1 and A2M, are specific expressed in FGFR2+ fibrocytes before arriving in tumor sites suggesting their possible roles in fibrocyte recruitment." (PMID 35941662, 2022). "In our study, we found a negative correlation between budding and the levels of CMKLR1 in the tumor and margin tissue." (PMID 34946244, 2021). "Using a transgenic mouse model overexpressing bioactive chemerin under the control of the keratin K5 promoter, we have shown recently that expression of chemerin by keratinocytes inhibits tumor development in the DMBA/TPA model, and this effect is mediated by the main receptor of chemerin, CMKLR1." (PMID 34638484, 2021). "In the B16 graft model, CMKLR1 invalidation had no influence by itself on the tumor growth but abrogated completely the effect of chemerin expression by the tumor cells." (PMID 34548907, 2021). "If chemerin gradients were still present in these mice, they should drive CMKLR1-expressing cells to the skin rather than to the tumor graft." (PMID 34548907, 2021). "We also demonstrated that tumor cells overexpressing CCRL2 can display chemerin on their surface in a stable manner, allowing them to trigger functional responses (calcium mobilization in this case) from cells expressing CMKLR1." (PMID 34638484, 2021). "In HCV-HCC chemerin is not regulated and CMKLR1 is already low in the non-tumor tissues of those patients." (PMID 33066325, 2020). "Regarding the anti-tumor effects of chemerin in experimental HCC models, drugs to enhance CMKLR1 abundance may reduce disease severity." (PMID 33066325, 2020). "CMKLR1 mRNA tended to be lower in tumor tissues of patients with non-viral HCC and protein expression was significantly reduced when compared to the respective para-tumorous tissues." (PMID 33066325, 2020). "CMKLR1 protein was reduced in tumor and non-tumor liver tissue of HCV patients in comparison to HBV and double infected patients." (PMID 33066325, 2020). "We have attempted to apply this method with a CMKLR1-targeting peptide but failed to improve tumor uptake above the level of unpurified tracer (about 6%, unpublished results)." (PMID 31163066, 2019). "This discrepancy raises the hypothesis that chemerin may act as a tumour suppressor through its binding to chemokine-like receptor 1 (CMKLR1) and G protein-coupled receptor 1 (GPR1) while potentially facilitating tumour progression by activating vascular endothelial growth." (PMID 40414892, 2025). "We found a negative correlation between the levels of MVD and CMKLR1 in the tumor and margin." (PMID 34946244, 2021). "In addition, CMKLR1 was found to correlate with GDF-15 and VEGF-A levels in CRC tumor-free margin." (PMID 35008289, 2021). "We observed that in the B16 syngeneic graft model, the absence of CMKLR1 reversed completely the effect of chemerin, whether chemerin is produced by the tumor cells or by the host keratinocytes." (PMID 34548907, 2021). "However, in our previous study, we did not observe any association between CMKLR1 and VEGF A levels in either the tumor or the margin tissue of CRC." (PMID 34946244, 2021). "Interestingly, CMKLR1 protein was low in tumor and non-tumor tissues of HCV infected patients in comparison to the respective tissues of HBV and HBV/HCV infected patients." (PMID 33066325, 2020). "Moreover, CMKLR1 protein was lower in the tumors than the adjacent non-tumor tissues of non-viral HCC patients, and tended to decrease in HBV-related tumors." (PMID 33066325, 2020). "CMKLR1 protein was not prognostic in these different tumor diseases." (PMID 31905933, 2019). "Similarly, CMKLR1 knockdown completely mitigated chemerin’s effect on tumor invasion and T cell mediated cytotoxicity, suggesting the functional significance of the chemerin/PTEN/PD-L1 axis in human tumor cells." (PMID 30400822, 2018).
tumor (continued). "Importantly, these tumor suppressive effects were specifically mediated by NK cells, as only NK cell depletion abrogated the effect, and required host expression of CMKLR1, as chemerin-expressing tumors showed accelerated growth in CMKLR1-negative mice." (PMID 31370263, 2019). "Sex-specific analysis showed that the CMKLR1 protein in the HCC tissues of females was not related to the T stage, lymph node invasion, vessel invasion, grading, tumor size, or UICC score." (PMID 36979716, 2023). "Notably, these experiments were conducted in the absence of chemerin and CMKLR1, indicating that the observed effects were independent of the chemerin/CMKLR1 axis and solely attributable to CCRL2 expression in tumor cells." (PMID 40867595, 2025).
cancer (30 papers, 2017 to 2025). A tumor composed of atypical neoplastic, often pleomorphic cells that invade other tissues. "The combination of chemerin and CMKLR1 can regulate the proliferation, migration and invasion of gastrointestinal and immune cells, as well as cancer-associated cells, and has the potential to become a new target for disease treatment." (PMID 40959100, 2025). "Published results indicate that chemerin promotes angiogenesis through CMKLR1, and this has been implicated in cancer progression." (PMID 39595036, 2024). "Previous studies suggest that the chemerin/CMKLR1 axis is the main signal transducing pathway of chemerin underlying its effect on cancer progression." (PMID 35459783, 2022). "CMKLR1’s role in metabolic diseases, inflammation, and cancer makes it an emerging target for PET imaging." (PMID 39911388, 2025). "The present study not only enriches the researches of chemerin in female malignant tumor development especially for omental metastasis but also reveals a novel mechanism of CMKLR1/RhoA/ROCK1-mediated EMT in invasion of metastasis of OC cells." (PMID 39104601, 2024). "Strikingly, its receptor, Cmklr1, is upregulated in macrophages upon co-culture with fibroblasts or in the presence of cancer CM." (PMID 37726308, 2023). "CMKLR1 agonists are being considered for their potential therapeutic use in some inflammatory diseases and cancer types." (PMID 35004698, 2021). "While chemerin is frequently downregulated in several cancer types, the chemerin receptor CMKLR1 is directly involved in the progression of some tumors." (PMID 34359687, 2021). "Chemerin, a multifunctional protein acting through the receptor ChemR23/CMKLR1, is downregulated in various human tumors and was shown to display antitumoral properties in mouse models of cancer." (PMID 34548907, 2021). "Various leukocyte populations involved in the host response to cancer (macrophages, dendritic cells, NK cells) express CMKLR1." (PMID 34548907, 2021). "Chemerin expression was analyzed in different human cancers, whereas levels of CMKLR1 were hardly investigated." (PMID 31905933, 2019). "CMKLR1, which was found to be up-regulated in cancer tissue (p = 0.005), positively affected OS of NSCLC patients (p = 3.5 × 10−6), but not FP." (PMID 31370263, 2019). "Thus, to further approach the possible role of chemerin and CMKLR1 in this cancer entity, analyses of their protein levels in OC cancer tissue and identification of correlated proteins are necessary." (PMID 36900088, 2023). "Along with other roles of chemerin revealed in cancer, such as angiogenesis and PD-L1/PD-1 axis regulation, focusing on chemerin/CMKLR1 axis blockade may help develop effective therapeutics targeting mesenchymal GBM." (PMID 35459783, 2022). "In addition, the chemerin (RARRES2 gene product)–CMKLR1 (chemokine-like receptor 1) axis has been reported to activate MSC migration to cancer tissue and damaged liver lesions." (PMID 35723360, 2022). "Chemerin may be an attractive shuttling system to selectively target cancer tissue overexpressing CMKLR1." (PMID 34359687, 2021). "This suggests that CMKLR1 could have a role in cancer, and in vitro studies are in agreement." (PMID 29279348, 2018). "We first studied the expression of CMKLR1 in BC and MPM, using the dataset of The Cancer Genome Atlas (TCGA), where these pathologies appear to express high level of CMKLR1 among 37 cancers analyzed." (PMID 37539056, 2023). "In cancer, however, the expression of CMKLR1, GPR1, and CCRL2 has not been studied to great extent." (PMID 35008289, 2021). "The investigators demonstrate that both CMKLR1 and GPR1 are involved in these processes, by selectively inhibiting these receptors and observing a significant but not complete suppression of cancer cell migration." (PMID 39590835, 2024). "Although most known functions of GPR1 are mediated by CMKLR1, the biological role of GPR1 in cancers has not been well explored, despite its involvement in metabolic processes." (PMID 35459783, 2022).
metabolic disease (12 papers, 2013 to 2025). A congenital disorder (due to inherited enzyme abnormality) or acquired (due to failure of a metabolically important organ) disorder resulting from an abnormal metabolic process. "Although we have not investigated the changes of the gut flora, our result is consistent with report by HJ, who reported that CMKLR1 KO is benefit for HFD induced metabolic diseases." (PMID 36624417, 2023).
cardiovascular disease (8 papers, 2016 to 2025). "Again, it has yet to be determined which receptor is mediating these effects, but they could also be means by which chemerin/CMKLR1 contribute to cardiovascular disease." (PMID 29279348, 2018). "Also in concordance with the emerging roles of CMKLR1 in the cardiovascular system, GPR1 has been linked to cardiovascular disease." (PMID 29279348, 2018).
infection (6 papers, 2011 to 2025). The state of being infected such as from the introduction of a foreign agent such as serum, vaccine, antigenic substance or organism. "Therefore, p4 is not likely to interfere with interactions between chemerin and CMKLR1, allowing chemerin to exert other actions, such as creating an infection-controlling environment through recruiting CMKLR1-expressing leukocytes." (PMID 34803962, 2021).
inflammation (5 papers, 2012 to 2024). Aberrant reaction of the microcirculation characterized by movement of fluid and leukocytes from the blood into extravascular tissues. "In this regard, Lin and colleagues demonstrated that deficiency of chemerin or intestinal epithelial cell–specific CMKLR1 conferred high susceptibility to microbiota-driven neutrophilic colon inflammation in mice following epithelial injury." (PMID 36883565, 2023). "In a separate model of acute lung inflammation, cigarette smoke-induced lung inflammation was attenuated in CMKLR1 deficient mice with decreased levels of inflammatory chemokines and inflammatory cells." (PMID 23293638, 2012). "Thus, if CMKLR2 exerts the opposite effect on O3‐induced lung injury and lung inflammation than that which occurs when CMKLR1 is absent, no net effect on any indice would manifest in CMKLR1‐deficient mice." (PMID 38631890, 2024). "Moreover, resolvin-E1-mediated resolution of OVA-induced airway inflammation is dependent upon NK cells that express CMKLR1, a resolvin E1 receptor." (PMID 23828644, 2013).
animal disease (1 paper, 2022). "Currently, antibodies for chemerin neutralization, synthetic chemerin peptide, small-molecule antagonists for CMKLR1 (α-NETA and CCX832), and nanobodies for CMKLR1 were developed, and these reagents were shown to display effective therapeutic effects in several animal disease models." (PMID 36009457, 2022).
CMKLR1 also shares sentences with these, for which no sentence is quoted: liver steatosis (6 papers); multiple sclerosis (4); endothelial dysfunction (3); experimental autoimmune encephalomyelitis (3); Hyperglycemia (3); myocardial infarction (3); peritonitis (3); aortic valve disease (2); chronic kidney disease (2); hyperlipidemia (2); ischemic stroke (2); myocardial ischemia (2); osteoarthritis (2); papilloma (2); pulpitis (2); status epilepticus (2); Stroke (2); acute myeloid leukemia (1); acute myocardial infarction (1); acute respiratory distress syndrome (1); adenoma (1); airway hyperresponsiveness (1); Anxiety (1); Arthritis (1); B-cell CLL (1); cardiac hypertrophy (1); Cerebral ischemia (1); cervical metaplasia (1); cholangiocarcinoma (1); Chronic Hepatitis C (1).
A further 47 diseases each share a sentence with CMKLR1 in 1 paper.